SCN1A (sodium voltage-gated channel alpha subunit 1)
Diseases named in the same sentence as SCN1A in open-access papers (continued):
Sharing a sentence is not in itself a finding about the gene and the disease.
migraine (65 papers, 2010 to 2026). "This study investigated SCN1A gene mutations and clinical symptoms in Japanese migraine patients with FHM type 3." (PMID 40003892, 2025). "The analysis indicated that 70% and 30% of neuronal migraine-associated genes are significantly enriched in inhibitory and excitatory neurons, respectively, considering that many genes (such as SCN1A and CACNA1A) are found in both neuron types." (PMID 38731230, 2024). "It has been shown that rare forms of familial migraine are caused by mutations in SCN1A, but few studies have directly examined the role of Nav channels in migraine." (PMID 31375062, 2019). "The results of the clinical investigation showed that most of the patients in whom the missense variant in SCN1A was detected had migraine symptoms with typical aura, such as visual, sensory, motor, and speech symptoms, and dizzy attacks, in addition to headache and paralysis." (PMID 40003892, 2025). "This aligns with previous studies linking rare genetic variants in ion channel-related genes, such as ATP1A2 and SCN1A, to familial forms of migraine, further supporting the hypothesis of migraine as a channelopathy." (PMID 40869402, 2025). "Our observation also shows a shared genetic profile between FHM and MRS: this is important when evaluating PRS in complex neurological traits because it suggests that the identification of variants in SCN1A not only increases the risk of migraine, but also of MRS." (PMID 37510386, 2023). "In addition to FHM, SCN1A mutations are also found in a very small number of sporadic hemiplegic migraine patients." (PMID 35002916, 2021). "This is particularly relevant as many patients may have a common polymorphism that changes the ratio of splice variants in SCN1A, and which may affect the dosage of some drugs that have been used to treat migraine (e.g. carbamazepine)." (PMID 28621020, 2017). "Our work raises the hypothesis that there may be a genetic association between SNPs in SCN1A that alter splicing and susceptibility to migraine, with genotypes favouring inclusion of the ‘N’ or ‘neonatal’ exon increasing risk." (PMID 28621020, 2017). "Finally, the role of the (p.Thr1174Ser) SCN1A gene variant in determining the association of recurrent episodes of migraine, PFP, and MRS remains unclear; thus, functional studies should be carried out to determine the variant-related risk." (PMID 37510386, 2023). "This may explain why migraine pain develops in carriers of SCN1A gain-of-function mutations." (PMID 34135733, 2021). "Familiar hemiplegic migraine type 3 (FHM3), which is caused by specific missense mutations in the SCN1A gene encoding the α1 subunit of voltage-gated NaV1.1 sodium channels, allows the specific interrogation of the role mutant NaV1.1 channels in migraine pathophysiology." (PMID 34135733, 2021). "Genes such as CACNA1A, ATP1A2, and SCN1A have played an instrumental role in shaping the genetic understanding of CSD and aura mechanisms and therefore migraine susceptibility." (PMID 37628876, 2023). "Previous attempts at determining key genes in migraine-associated vertigo suggest the involvement of ion channel genes, such as CACNA1A, ATP1A2, and SCN1A." (PMID 37107589, 2023). "Hemiplegic migraine (HM) is a rare form of migraine, defined by headache associated with transient hemiplegia, and can be caused by mutations in either CACNA1A, ATP1A2, or SCN1A." (PMID 34135856, 2021). "Gain-of-function mutations of NaV1.1 (SCN1A) cause familial hemiplegic migraine type-3 (FHM3), a subtype of migraine with aura, of which CSD is the neurophysiological correlate." (PMID 34491914, 2021). "DNA sequencing of candidate genes in genomic regions shared by affected family members, have identified causal mutations in three hemiplegic migraine genes: CACNA1A (FHM1), ATP1A2 (FHM2), SCN1A (FHM3)." (PMID 32503413, 2020).
migraine (continued). "More recently, it has been shown that the SCN1A gene is also the target of mutations responsible for familial hemiplegic migraine (FHM-3), a rare autosomal dominant subtype of migraine with aura." (PMID 30038559, 2018). "Other genetic factors relating to migraine are associated with missense mutations of ATP1A2 (the Na+/K+ ATPase ion channel pump α2 subunit; FHM2) and SCN1A (Nav1.1 sodium channel; FHM3)." (PMID 23500200, 2013). "While pathogenic missense variants in CACNA1A, ATP1A2, and SCN1A can cause FHM or its sporadic form, they explain less than 20% of suspected hemiplegic migraine cases, suggesting the involvement of other genes or genetic variations, potentially including copy number variations (CNVs)." (PMID 42193281, 2026). "In contrast, CALCA and PRDM16 polymorphisms showed moderate evidence, and GRIA1 and SCN1A showed weaker evidence to explain nonresponsive migraine patients to Triptan treatment." (PMID 41121943, 2025). "In terms of genetic markers, mutations in CACNA1A, ATP1A2, and SCN1A are closely associated with FHM, while variants in NOTCH3 and TREX1 genes have been linked to migraine and its associated cerebrovascular diseases (e.g., cerebral arteriolar dominant disorders)." (PMID 39958329, 2025). "As a result, the genetic load may affect the severity and patterns of CSD, for instance, familial hemiplegic migraine (FHM1,2), a rare form of migraine with aura, was found to have a mutation in CACNA1A, ATP1A2, and the SCN1A gene, respectively." (PMID 36421543, 2022). "This applies to the four canonical FHM genes (CACNA1A, ATP1A2, SCN1A, and PRRT2), as well as the other genes reported to cause syndromes which may present with migraine." (PMID 36044383, 2022). "For example, splice variation in calcium channel pore-forming α1-subunit gene has been associated with familial hemiplegic migraine, and sodium voltage-gated channel alpha subunit 1 (SCN1A) has been associated with migraine without aura." (PMID 35453627, 2022). "Our patients who had ATP1A2 or SCN1A mutations also showed recurrent ataxia, vertigo/dizziness, and interictal nystagmus without hemiplegic migraine." (PMID 29062094, 2017). "We have identified a novel FHM-linked M1500V mutation in SCN1A, putatively affecting the inactivation loop of the sodium channel protein and confirming previous reports found the S231P mutation in KCNK18 in a patient with migraine with aura." (PMID 26747084, 2016). "The novel intronic polymorphism identified in a family with a CADASIL-like phenotype and migraine could affect the splicing of SCN1A transcript." (PMID 26747084, 2016). "Gene‐targeted mouse models of S/FHM Scn1a/NaV1.1 variants have been generated and they show facilitated/spontaneous generation of cortical spreading depolarization, a proposed pathological mechanism of migraine with aura, but no seizures." (PMID 37654020, 2024). "Interestingly, these genes have been also associated with neurological symptoms other than migraine, such as ataxia, nystagmus, and febrile comas for CACN1A (responsible for FHM1), and transient blindness and early onset seizures for SCN1A (responsible for FHM3)." (PMID 37510386, 2023). "Currently, we know of the following monogenic forms of migraine: Familial hemiplegic migraine type 1 (FHM1; mutations in the calcium channel gene CACNA1A), type 2 (FHM2; mutations in the sodium/potassium-transporting ATPase gene ATP1A2) and type 3 (FHM3; mutations in the sodium channel gene SCN1A)." (PMID 35785356, 2022). "In a female patient with migraine without aura and with onset at puberty, we found a novel intronic polymorphism possibly affecting alternative splicing of SCN1A, at 2:166852491, g.77659T>C, c.4581+32A>G, located between exons 24 and 25, in a region encoding inactivation loop of the channel." (PMID 26747084, 2016).
migraine (continued). "Familial hemiplegic migraine (FHM) is a rare, monogenic, autosomal dominant subtype of migraine, in which three genes, CACNA1A, ATP1A2, and SCN1A, are currently known to be involved." (PMID 30498473, 2018). "Until now, three undisputed hemiplegic migraine genes, CACNA1A (FHM1), ATP1A2 (FHM2), SCN1A (FHM3), have been identified; despite recent technical advances in whole genome/whole exon next generation sequencing no additional hemiplegic migraine genes have been identified." (PMID 34112082, 2021). "Comparably, a much smaller number of SCN1A mutations has been found to be linked to FHM3 (12 mutations so far), and the genotype-phenotype correlation for migraine mutations is not fully clear." (PMID 31730442, 2019). "So far, SCN1A gene has never been investigated in subjects with common forms of migraine." (PMID 21713554, 2011). "Molecular analysis of the CACNA1A and ATP1A2 genes in patients with migraine without aura and with aura, has shown that these two genes are not involved in common forms of migraine, although similar studies have not examined the SCN1A gene." (PMID 21713554, 2011).
familial hemiplegic migraine (60 papers, 2009 to 2025). "Genetic factors play a significant role, with mutations in genes like CACNA1A, ATP1A2, and SCN1A implicated in familial hemiplegic migraine, a rare subtype, and potentially contributing to broader aura susceptibility through ion channel dysfunction." (PMID 40873917, 2025). "Genetic studies have identified several ion channel genes, including CACNA1A, ATP1A2, and SCN1A, which encode ion channels and transport proteins, as possible causes or contributors to familial hemiplegic migraine (FHM)." (PMID 38068897, 2023). "Heritability seems to be more eminent in MwA subtype than MwoA, further supported by the identification of mutations in three ion transporter genes (CACNA1A, ATP1A2, and SCN1A) associated with familial hemiplegic migraine (FHM); a rare monogenic form of MwA." (PMID 36698892, 2022). "Mutations in the ion transport genes CACNA1A, ATP1A2 and SCN1A can lead to familial hemiplegic migraine, indicating genetic heterogeneity." (PMID 34384358, 2021). "In fact, mutations of the SCN1A gene that codes for NaV1.1 have been associated with familial hemiplegic migraine suggesting a likely role in nociception." (PMID 26690478, 2015). "Mutations in CACNA1A, ATP1A2 and SCN1A genes have been associated with familial hemiplegic migraine (FHM), a rare monogenic form of migraine." (PMID 23566281, 2013). "Mutations in three genes encoding neural ion channels, CACNA1A, ATP1A2, and SCN1A, have been described in patients with familial hemiplegic migraine (FHM), a rare monogenic, autosomal dominant form of migraine with aura." (PMID 21344296, 2011). "Indeed, mutations in SCN1A (the gene for Nav1.1) have been associated with inherited epileptic syndromes and familial hemiplegic migraine in humans." (PMID 21345196, 2011). "This is the case of PMM2-CDG and some channelopathies related to CACNA1A, ATP1A2, and SCN1A mutations, leading to episodes called familial hemiplegic migraine (FHM)." (PMID 34708008, 2021). "HM is categorised based on family history, with familial hemiplegic migraine (FHM) linked to pathogenic variants in the CACNA1A, ATP1A2, and SCN1A ion transport genes." (PMID 40725463, 2025). "Genetic studies have identified several mutations associated with familial hemiplegic migraine, including CACNA1A (FHM1), ATP1A2 (FHM2), and SCN1A (FHM3)." (PMID 41552155, 2025). "SCN1A-related disorders do cover a wide spectrum of clinical presentations, ranging from familial hemiplegic migraines to severe developmental epileptic encephalopathy, highlighting the variable expressivity and incomplete penetrance recorded with this gene." (PMID 38891831, 2024). "Familial hemiplegic migraine (FHM) is a severe neurogenetic disorder for which three causal genes, CACNA1A, SCN1A, and ATP1A2, have been implicated." (PMID 35928792, 2022). "Familial hemiplegic migraine (FHM) is a monogenic autosomal dominant subtype of migraine with aura, which is caused by mutations in three genes, which are CACNA1A, ATP1A2, and SCN1A." (PMID 35281991, 2021). "The calcium channel gene, CACNA1A, has been identified as a key gene in which mutations can cause familial hemiplegic migraine (FHM), along with several other FHM-related ion channel genes (ATP1A2, SCN1A)." (PMID 32233732, 2020). "Both conditions share potential genetic underpinnings, with genes associated with familial hemiplegic migraine (such as CACNA1A, ATP1A2, and SCN1A) implicated in certain aura subtypes, though evidence for genetic influences is more robust in MA due to larger-scale studies." (PMID 40873917, 2025). "Familial hemiplegic migraine (FHM), an autosomal dominant hereditary form of HM, is linked to mutations in specific genes (CACNA1A, ATP1A2, SCN1A) that encode ion channels and transporters critical for neuronal excitability and synaptic transmission." (PMID 40264646, 2025).
familial hemiplegic migraine (continued). "The genetic basis for CSD is supported by its strong association with familial hemiplegic migraine (FHM), where mutations in genes, such as CACNA1A, ATP1A2, and SCN1A, alter ion channel function, predisposing the brain to hyperexcitability." (PMID 40869402, 2025). "Familial hemiplegic migraine (FHM), which is a subtype of migraine with aura, is caused by mutations in CACNA1A, ATP1A2, and SCN1A." (PMID 33193064, 2020). "Moreover, the Q1489H missense substitution on SCN1A encoding the Nav1.1 neuronal voltage-gated Na+ channel (the Q1475 homolog in Nav1.5) is highly expressed in the central nervous system, including the retina, and is found in patients with familial hemiplegic migraine (FHM)." (PMID 24098284, 2013). "On the other hand, mutations in the four genes (CACNA-1A, ATP1A2, SCN1A, and PRRT2) identified in patients with familial hemiplegic migraine (FHM) are associated with a reduced threshold value of cortical spreading depression, which is also responsible for auras." (PMID 37048668, 2023). "Familial hemiplegic migraine (FHM) is an autosomal dominant disorder, classified into 3 subtypes, based on the gene involved (CACNA1A in FHM1, ATP1A2 in FHM2 and SCN1A in FHM3)." (PMID 34320921, 2021). "An Italian family with familial hemiplegic migraine (FHM) with the absence of mutations in the known genes associated with this disorder, namely ATP1A2, ATP1A3, CACNA1A, and SCN1A, has recently been reported." (PMID 32549268, 2020). "Previous hypotheses of molecular mechanisms in migraine have come from familial hemiplegic migraine (FHM), a rare Mendelian form of the disease, where three ion channel genes are known to be involved (CACNA1A, ATP1A2, and SCN1A)." (PMID 27543003, 2016). "Indeed, one might reasonably screen the other familial hemiplegic migraine genes FHM2 (ATP1A2), FHM3 (SCN1A) along with FHM1 (CACNA1A) in case these are responsible for EA2‐like symptoms in a patient." (PMID 27066515, 2016). "The most established molecular knowledge of migraine comes from mutations in the three genes for familial hemiplegic migraine (FHM) – CACNA1A, ATP1A2 and SCN1A." (PMID 23675283, 2013).
Seizure (54 papers, 2009 to 2026). A seizure is an intermittent abnormality of nervous system physiology characterized by a transient occurrence of signs and/or symptoms due to abnormal excessive or synchronous neuronal activity in the brain. "Seizures resulting from SCN1A loss of function limit inhibitory neuron excitability, thereby disinhibiting excitatory pyramidal cells." (PMID 40662949, 2025). "Seizures begin a few months after birth and in 80% of patients are caused by a mutation in the Scn1a gene, encoding the alpha subunit of the voltage-gated sodium channel Nav1.1." (PMID 36769051, 2023). "Clinical presentation of SCN1A mutations ranges from febrile seizures and benign febrile seizures plus (FS/FS+) to severe epilepsy syndrome such as DRVT." (PMID 36672274, 2023). "Collectively, these results suggest that Scn1a KO deficiency significantly aggravated the susceptibility and severity of seizures and exacerbated cognitive dysfunction." (PMID 32184723, 2020). "The functional significance of Lira in the susceptibility to Scn1a KO induced-epileptic seizures was investigated." (PMID 32184723, 2020). "For both “ABCA4 –Macular dystrophy—recessive” and “SCN1A –Seizures—dominant”, bins showing strong association correctly clustered with rare variants (GF < 0.00025)." (PMID 32271766, 2020). "Seizures can damage the brain, and the SCN1A gene mutation can lead to abnormal brain development." (PMID 38203200, 2023). "SCN1A haploinsufficiency producing Nav1.1 dysfunction mainly affects GABAergic neurons, which according to the affected site, cortex, cerebellum, basal ganglia, or hypothalamus, are the cause of epileptic seizure, ataxia, crouching gait, thermal dysregulation, and sleep disturbances." (PMID 29764460, 2018). "We present the case of a five-and-a-half-month-old boy with SCN1A gene-related epileptic seizures, starting as focal seizures and progressing to generalized tonic-clonic seizures." (PMID 39119390, 2024). "Seizure frequency is often quantified in Scn1a+/− mice to assess the anticonvulsant efficacy of a novel treatment." (PMID 36811143, 2023). "Seizures were, on average, less intractable than in SCN1A-DS, and patients above six years of age (9/12 patients) had less than 4 seizures a year with one patient who was free of seizures at the time of the study." (PMID 19214208, 2009). "Moreover, it is advisable to avoid introducing OXC for some genetic epilepsy, particularly in SCN1A-related Dravet syndrome, in spite of its prominent characteristics of focal seizures." (PMID 35720076, 2022). "Seizures typically originate in the cortex, and it is not clear whether brainstem respiratory function is compromised directly by loss of Scn1a or indirectly by descending seizure activity." (PMID 40924494, 2025). "Six in-frame deletions in SCN1A were identified in our cases with SMEI, generalized epilepsy with febrile seizures plus (GEFS+), partial epilepsy with febrile seizures plus (PEFS+) and Lennox–Gastaut syndrome (LGS)." (PMID 35359575, 2022). "Seizures were observed in all vehicle-treated WT littermates (11 RS2) and Scn1a+/− mutants (1 RS1, 9 RS2, 1 RS3)." (PMID 27799911, 2016). "While in a proportion of patients with focal seizures the disorder is associated with focal cortical dysplasia and/or monoallelic variants in the genes encoding the mTOR inhibitory GATOR1 complex, neither SCN9A nor SCN1A have been associated with this seizure type." (PMID 33216760, 2020).